VCF2 (VCP nuclear cofactor family member 2)
Synonyms: CXorf44; FAM104B; FLJ20434
Tractability: No criterion of Open Targets' tractability assessment is met for any kind of drug.
Gene: Protein-coding gene on chromosome X (55,143,102 to 55,161,310, reverse strand). Ensembl gene ENSG00000182518.
Homologues: Orthologues: macaque VCF2 (89% identical), mouse Vcf1 (57% identical), rat Vcf2 (47% identical).
Diseases named in the same sentence as VCF2 in open-access papers:
VCF2 is named in the same sentence as 4 diseases in open-access papers, as found by Europe PMC text mining. Sharing a sentence is not in itself a finding about the gene and the disease.
VCF2 shares sentences with these, for which no sentence is quoted: Alzheimer disease (1 paper); amyotrophic lateral sclerosis (1); neurodegenerative disease (1); neuromuscular disease (1).